ATP1A2 (ATPase Na+/K+ transporting subunit alpha 2)
Description:
Catalytic subunit of the Na(+)/K(+)-ATPase that hydrolyzes ATP to exchange ions across the plasma membrane, exporting 3 Na(+) and importing 2 K(+) per cycle. It undergoes ATP-driven conformational changes that allow alternating binding and release of Na(+) and K(+) ions across the membrane (By similarity). This process maintains essential Na(+) and K(+) gradients for membrane potential and cellular function.
Synonyms: FHM2; DEE98; FARIMPD; MHP2
Tractability: Small molecule: an approved drug acts on it; a high-quality ligand is known; it belongs to a druggable protein family. Antibody: UniProt places it where antibodies can reach, with high confidence; its Gene Ontology location is reachable by antibodies, with high confidence; UniProt predicts a signal peptide or a membrane-spanning region. PROTAC: ubiquitination databases record sites on it; its protein half-life has been measured; a small molecule that binds it is known.
Safety:
Unwanted effects reported when the protein is acted on. In parentheses: how it was acted on, where the effect was seen, and who reports it.
atrioventricular block (inhibition, acute dosing; renal, cardiovascular; source: Lynch et al. (2017))
cardiac arrhythmia (inhibition, acute dosing; renal, cardiovascular; source: Lynch et al. (2017))
decreased heart rate (inhibition, acute dosing; renal, cardiovascular; source: Lynch et al. (2017))
increased cardiac contractility (inhibition, acute dosing; renal, cardiovascular; source: Lynch et al. (2017))
increased urinary sodium excretion (inhibition, acute dosing; renal, cardiovascular; source: Lynch et al. (2017))
increased urine excretion (inhibition, acute dosing; renal, cardiovascular; source: Lynch et al. (2017))
ventricular fibrillation (inhibition, acute dosing; renal, cardiovascular; source: Lynch et al. (2017))
vomiting (inhibition, acute dosing; renal, cardiovascular; source: Lynch et al. (2017))
Gene: Protein-coding gene on chromosome 1 (160,115,758 to 160,143,595, forward strand). Ensembl gene ENSG00000018625.
Subcellular location: Membrane; Cell membrane
Pathways (Reactome):
Disease: Potential therapeutics for SARS
Muscle contraction: Ion homeostasis
Transport of small molecules: Ion transport by P-type ATPases
Gene Ontology:
Molecular function: ATP binding; ATP hydrolysis activity; ATPase-coupled monoatomic cation transmembrane transporter activity; P-type sodium:potassium-exchanging transporter activity; potassium ion binding; protein binding; protein-folding chaperone binding; sodium ion binding; steroid binding; steroid hormone binding; phosphatase activity; nucleotide binding; P-type potassium transmembrane transporter activity; protein heterodimerization activity
Biological process: ATP metabolic process; cellular response to steroid hormone stimulus; intracellular potassium ion homeostasis; intracellular sodium ion homeostasis; monoatomic cation transmembrane transport; potassium ion import across plasma membrane; potassium ion transmembrane transport; sodium ion export across plasma membrane; sodium ion transmembrane transport; amygdala development; behavioral fear response; cardiac muscle contraction; cell communication by electrical coupling involved in cardiac conduction; locomotion; locomotory exploration behavior; membrane depolarization during cardiac muscle cell action potential; membrane repolarization; negative regulation of calcium ion transmembrane transport; negative regulation of cytosolic calcium ion concentration; negative regulation of heart contraction; neurotransmitter uptake; olfactory cortex development; positive regulation of heart contraction; potassium ion transport; proton transmembrane transport; and 19 more
Cellular component: cytoplasm; extracellular vesicle; membrane; organelle membrane; plasma membrane; sodium:potassium-exchanging ATPase complex; T-tubule; cell projection; neuronal cell body; caveola; cell surface; dendritic spine; endoplasmic reticulum; endosome; intercalated disc; sarcolemma
Genetic constraint (gnomAD): Loss-of-function variants: 56 observed, 117.01 expected, observed/expected ratio (o/e) 0.48, 90% interval 0.38 to 0.6. The upper end of that interval is the gene's LOEUF score, 0.6, which puts it in group 2 of 6, group 1 being the genes least tolerant of losing a copy. Missense variants: 712 observed, 1,416.5 expected, observed/expected ratio (o/e) 0.5, 90% interval 0.47 to 0.54. Synonymous variants: 490 observed, 551.12 expected, observed/expected ratio (o/e) 0.89, 90% interval 0.82 to 0.96.
Gene-disease validity (ClinGen):
ClinGen rates the evidence that ATP1A2 causes each of these diseases.
fetal akinesia, respiratory insufficiency, microcephaly, polymicrogyria, and dysmorphic facies (autosomal recessive): Definitive.
hemiplegic migraine-developmental and epileptic encephalopathy spectrum (autosomal dominant): Definitive. A spectrum in which individuals may present with phenotypes ranging from hemiplegic migraines without epilepsy to developmental and epileptic encephalopathy with or without episodic hemiplegia or other forms of paresis.
Homologues: Orthologues: chimpanzee ATP1A2 (100% identical), guinea pig ATP1A2 (99% identical), mouse Atp1a2 (99% identical), rat Atp1a2 (99% identical), rabbit ATP1A2 (99% identical), dog ATP1A2 (95% identical), pig ATP1A2 (94% identical), tropical clawed frog atp1a2 (93% identical), zebrafish atp1a2a (86% identical), Caenorhabditis elegans catp-3 (38% identical), Caenorhabditis elegans catp-2 (37% identical), Drosophila melanogaster SPoCk (25% identical), and 6 more. Paralogues in human: ATP1A1 (87% identical), ATP1A3 (87% identical), ATP1A4 (79% identical), ATP12A (65% identical), ATP4A (63% identical), ATP2A1 (30% identical), ATP2A2 (30% identical), ATP2B2 (30% identical), ATP2B3 (29% identical), ATP2A3 (29% identical), ATP2B1 (29% identical), ATP2B4 (28% identical), and 9 more.
Diseases named in the same sentence as ATP1A2 in open-access papers:
ATP1A2 is named in the same sentence as 127 diseases in open-access papers, as found by Europe PMC text mining. Sharing a sentence is not in itself a finding about the gene and the disease. The quoted sentences say what the papers report.
migraine (82 papers, 2005 to 2026). "Variants in ATP1A2 are associated with various forms of migraine, and with epilepsy and developmental and epileptic encephalopathy type 98 (DEE98)." (PMID 39859528, 2025). "Our data suggest that the prevalent clinical manifestations of the ATP1A2 c.1844G > A PV is migraine with typical aura associated with psychiatric disorders." (PMID 39723107, 2025). "Mutations in ATP1A2 lead to disruptions in ion homeostasis and neuronal excitability, contributing to the development and onset of migraine attacks." (PMID 37628876, 2023). "They conducted a mutation analysis of AT1PA2; the results revealed that two Belgian families had two novel ATP1A2 mutations, and both of these mutations occurred in families who experienced migraine and epilepsy." (PMID 37628876, 2023). "Similar episodes have been reported in patients affected by hemiplegic migraine, especially from ATP1A2 mutations." (PMID 35897016, 2022). "Relevant in migraine, however, is that the many regulators of Na+, K+-ATPase ranging from local brain cations to adrenaline, serotonin, and estrogen are known to fluctuate in migraine, and mutation in the ATP1A2 gene underlies FHM2." (PMID 31173612, 2019). "ATP1A2 is highly expressed in the brain, and has been implicated in cortical spreading depression and migraines." (PMID 30154697, 2018). "Familial hemiplegic migraine type 2 (FHM2) is a rare subtype of migraine caused by mutations in the ATP1A2 gene, encoding the α2 isoform of the Na+/K+-ATPase, predominantly expressed in astrocytes." (PMID 30446731, 2018). "Here we report, for the first time, an exonic duplication in the ATP1A2 associated with hemiplegic migraine." (PMID 28593511, 2017). "We report here for the first time the identification of an exonic duplication in the ATP1A2 associated with hemiplegic migraine." (PMID 28593511, 2017). "To date, about 81 ATP1A2 mutations have been reported in migraine-correlated neurological disease cases in the literature." (PMID 27445835, 2016). "More recently, a variant of ATP1A2 has been associated in a Korean family with a new form of progressive hearing loss with migraine." (PMID 27083884, 2016). "Lastly, the association between ATP1A2 SNPs and migraine status was tested using a fully adjusted logistic regression model accounting for the same risk factors." (PMID 23459313, 2013). "The case report presented in this paper describes a mutation in the ATP1A2 and prothrombin genes in a young adolescent with sporadic hemiplegic migraine." (PMID 24396618, 2013). "Mutations and deficiencies in Atp1a2 are associated with FHM2 in patients suffering from migraines with hemiplegia and partial paralysis during the aura phase." (PMID 23561701, 2013). "Since the discovery of FHM-2, a disorder caused by mutations in the ATP1A2 gene at the C1q23 locus, this region has been the focus of intense genetic research for the more common types of migraine." (PMID 17727731, 2007). "ATP1A2 encodes a Na+/K + ATPase subunit crucial for ion balance, and disruptions can impact pain processing and heighten the risk of pain or neurological issues such as migraine later in life." (PMID 40313396, 2025). "Therefore, it is likely that the activation of astrocytes causes migraine by a similar mechanism to Atp1a2+/− mice." (PMID 32237043, 2020). "Astrocytes with elevated Ca2+ concentrations, our novel findings in Atp1a2+/− mice, could cause the migraine aura and headache through vasodilation and inflammatory responses in FHM, although it remains to be elucidated." (PMID 32237043, 2020). "Then, a survey is given about ATP1A2 mutations implicated in migraine cases as documented in the literature with focus on mutations that were described to completely destroy enzyme function, or lead to misfolded or mistargeted protein in particular model cell lines." (PMID 27445835, 2016).
migraine (continued). "A genome-wide linkage scan showed a susceptibility locus for common migraine on chromosome 1q, and ATP1A2 (or a flanking gene) was hypothesized to be involved in common migraine besides FHM258." (PMID 26911348, 2016). "ATP1A2 mutations may also underlie basilar migraine (BM), which is a subtype of migraine with aura originating from the brainstem or involvement of both hemispheres." (PMID 24904274, 2014). "This case illustrates the presence of a mutation in the ATP1A2 gene of unknown significance in a patient with sporadic hemiplegic migraine." (PMID 24396618, 2013). "To further explore these observations, we assessed the association between ATP1A2 polymorphisms, migraine, and the risk of ischemic stroke in participants of the Genetics of Early-Onset Stroke Study, a population-based case–control study of ischemic stroke among men and women aged 15–49." (PMID 23459313, 2013). "To test this hypothesis we assessed the association between ATP1A2 single nucleotide polymorphisms (SNPs), migraine, and the risk of ischemic stroke in a previously collected biracial case–control sample of young-onset ischemic stroke." (PMID 23459313, 2013). "This case report describes a young woman with sporadic hemiplegic migraine that was found to have a mutation of unknown significance (c.2273 G>C) in the ATP1A2 gene and a heterozygous prothrombin G20210A mutation." (PMID 24396618, 2013). "Our study was motivated by the fact that prior studies have shown that the ATP1A2 gene is implicated in rare forms of migraine (familial hemiplegic migraine type II) which has features typical of migraine with aura in addition to features consistent with transient brain ischemia." (PMID 23459313, 2013). "Thus ATP1A2 mutations affect glutamatergic neurotransmission, causing the defective regulation of the balance of excitation and inhibition in the brain as seen in migraine." (PMID 38273253, 2024). "Given the shared mechanisms between migraine and epilepsy, both episodic disorders of the brain and the ability of one to trigger the other, Deprez and colleagues studied whether mutations in ATP1A2 are common for both migraine patients and epilepsy patients." (PMID 37628876, 2023). "The numbers of astrocytes with elevated Ca2+ concentrations in Atp1a2+/− (11.0 ± 2.8 astrocytes) were larger than those in wild‐type mice (5.7 ± 2.5 astrocytes) after induction of cortical spreading depression (which is closely associated with migraine) by application of KCl." (PMID 32237043, 2020). "For instance, alterations in neurotransmitters such as glutamate and GABA; CSD; and mutations in genes including CACNA1A, ATP1A2, and SCN1A have been shown to be highly correlated with both migraine and epilepsy." (PMID 41404467, 2025). "Pathogenic variants of ATP1A2 result in different disorders, such as familial hemiplegic migraine type 2 (FHM2) (602481) and migraine, familial basilar (OMIM 602481)." (PMID 37240249, 2023). "Previous attempts at determining key genes in migraine-associated vertigo suggest the involvement of ion channel genes, such as CACNA1A, ATP1A2, and SCN1A." (PMID 37107589, 2023). "Genes such as CACNA1A, ATP1A2, and SCN1A have played an instrumental role in shaping the genetic understanding of CSD and aura mechanisms and therefore migraine susceptibility." (PMID 37628876, 2023). "Familial hemiplegic migraine (FHM) is a monogenic autosomal dominant subtype of migraine with aura, which is caused by mutations in three genes, which are CACNA1A, ATP1A2, and SCN1A." (PMID 35281991, 2021). "Hemiplegic migraine (HM) is a rare form of migraine, defined by headache associated with transient hemiplegia, and can be caused by mutations in either CACNA1A, ATP1A2, or SCN1A." (PMID 34135856, 2021). "DNA sequencing of candidate genes in genomic regions shared by affected family members, have identified causal mutations in three hemiplegic migraine genes: CACNA1A (FHM1), ATP1A2 (FHM2), SCN1A (FHM3)." (PMID 32503413, 2020).
migraine (continued). "Familial hemiplegic migraine type 1 (FHM1) is a form of migraine with aura caused by heterozygous mutations in 4 genes: CACNA1A, ATP1A2, SNC1A and PRRT2, but further heterogeneity is expected." (PMID 30167989, 2018). "The PAD gene list relates to a diverse set of human diseases, including cardiovascular (LMNA, MYH7), cystic fibrosis (CFTR), diabetes (HNF4A, IRS1) and migraine (ATP1A2)." (PMID 25611800, 2015). "Other genetic factors relating to migraine are associated with missense mutations of ATP1A2 (the Na+/K+ ATPase ion channel pump α2 subunit; FHM2) and SCN1A (Nav1.1 sodium channel; FHM3)." (PMID 23500200, 2013). "It is the only migraine disorder where pathogenetic mutations are known, since it is associated with mutations in the CANA1A, ATP1A2, and SCN1A genes." (PMID 24396618, 2013). "Previous studies have excluded the role of the two FHM genes (CACN1A, ATP1A2) in the common forms of migraine." (PMID 21713554, 2011). "While pathogenic missense variants in CACNA1A, ATP1A2, and SCN1A can cause FHM or its sporadic form, they explain less than 20% of suspected hemiplegic migraine cases, suggesting the involvement of other genes or genetic variations, potentially including copy number variations (CNVs)." (PMID 42193281, 2026). "This aligns with previous studies linking rare genetic variants in ion channel-related genes, such as ATP1A2 and SCN1A, to familial forms of migraine, further supporting the hypothesis of migraine as a channelopathy." (PMID 40869402, 2025). "In terms of genetic markers, mutations in CACNA1A, ATP1A2, and SCN1A are closely associated with FHM, while variants in NOTCH3 and TREX1 genes have been linked to migraine and its associated cerebrovascular diseases (e.g., cerebral arteriolar dominant disorders)." (PMID 39958329, 2025). "The association between familial hemiplegic migraine-related genes (CACNA1A, ATP1A2, and SCN1A) and both migraine and epilepsy, as well as the impact of polymorphisms in pain-related sodium channels SCN9A and SCN10A on migraine chronification, have been further elucidated." (PMID 41404467, 2025). "This applies to the four canonical FHM genes (CACNA1A, ATP1A2, SCN1A, and PRRT2), as well as the other genes reported to cause syndromes which may present with migraine." (PMID 36044383, 2022). "As a result, the genetic load may affect the severity and patterns of CSD, for instance, familial hemiplegic migraine (FHM1,2), a rare form of migraine with aura, was found to have a mutation in CACNA1A, ATP1A2, and the SCN1A gene, respectively." (PMID 36421543, 2022). "Currently, we know of the following monogenic forms of migraine: Familial hemiplegic migraine type 1 (FHM1; mutations in the calcium channel gene CACNA1A), type 2 (FHM2; mutations in the sodium/potassium-transporting ATPase gene ATP1A2) and type 3 (FHM3; mutations in the sodium channel gene SCN1A)." (PMID 35785356, 2022). "In the first two families in which FHM was associated to mutations in ATP1A2, six several affected individuals presented a history of seizures independent of hemiplegic migraine attacks; the penetrance of epilepsy is also incomplete in these families." (PMID 28593511, 2017). "Nor is there a large set of causal genes, except for three genes (CACNA1A, ATP1A2 and SCN1A) that have been identified for FHM, that can guide gene identification efforts in the common forms of migraine." (PMID 26899160, 2016). "ATP1A2 mutations lead to FHM2, a severe subtype of migraine with aura and temporary hemiparesis." (PMID 24904274, 2014). "This case had, in addition to a mutation in the ATP1A2 gene, a heterozygous prothrombin gene mutation, which so far has never been described in patients with sporadic hemiplegic migraine." (PMID 24396618, 2013). "We did not observe an association between any ATP1A2 polymorphisms and migraine as defined by this study." (PMID 23459313, 2013).